LINC00906 (long independently transcribed non-coding RNA 906)
Gene: Long non-coding RNA gene on chromosome 19 (28,883,430 to 28,970,874, forward strand). Ensembl gene ENSG00000267339.
Diseases named in the same sentence as LINC00906 in open-access papers:
LINC00906 is named in the same sentence as 2 diseases in open-access papers, as found by Europe PMC text mining. Sharing a sentence is not in itself a finding about the gene and the disease. The quoted sentences say what the papers report.
glioma (2 papers, 2023 to 2024). A benign or malignant brain and spinal cord tumor that arises from glial cells (astrocytes, oligodendrocytes, ependymal cells). "Furthermore, we examined the expression of the signature lncRNAs in cell lines U251 and T98G as tumor group, SVGp12 as normal or control group, by qPCR analysis, showing that the expression of CPB2-AS1, MIR155HG, LINC00906 and WDR11-AS1 were low in gliomas cells." (PMID 37153654, 2023).
LINC00906 also shares sentences with these, for which no sentence is quoted: tumor (1 paper).